GAD1 (glutamate decarboxylase 1)
Description:
Catalyzes the synthesis of the inhibitory neurotransmitter gamma-aminobutyric acid (GABA) with pyridoxal 5'-phosphate as cofactor. [Isoform 3]: Enzymatically inactive as glutamate decarboxylase.
Synonyms: GAD-67; GAD; CPSQ1; DEE89; SCP
Tractability: Small molecule: a structure with a bound ligand is known; it has a high-quality binding pocket. Antibody: its Gene Ontology location is reachable by antibodies, with high confidence; the Human Protein Atlas places it where antibodies can reach. PROTAC: ubiquitination databases record sites on it; its protein half-life has been measured.
Target class: Enzyme; Lyase
Gene: Protein-coding gene on chromosome 2 (170,813,213 to 170,861,151, forward strand). Ensembl gene ENSG00000128683.
Subcellular location (Human Protein Atlas): Cytosol; Plasma membrane; Vesicles
Pathways (Reactome):
Neuronal System: GABA synthesis; GABA synthesis, release, reuptake and degradation
Gene Ontology:
Molecular function: glutamate decarboxylase activity; identical protein binding; protein binding; carbon-carbon lyase activity; carboxy-lyase activity; pyridoxal phosphate binding
Biological process: gamma-aminobutyrate shunt; chemical synaptic transmission; gamma-aminobutyric acid biosynthetic process; L-glutamate catabolic process
Cellular component: clathrin-sculpted gamma-aminobutyric acid transport vesicle membrane; cytoplasm; plasma membrane; presynaptic active zone; vesicle membrane; axon; axon terminus; cell cortex; GABA-ergic synapse; inhibitory synapse; neuron projection terminus; perinuclear region of cytoplasm; presynapse; synapse
Genetic constraint (gnomAD): Loss-of-function variants: 26 observed, 63.43 expected, observed/expected ratio (o/e) 0.41, 90% interval 0.3 to 0.57. The upper end of that interval is the gene's LOEUF score, 0.57, which puts it in group 2 of 6, group 1 being the genes least tolerant of losing a copy. Missense variants: 439 observed, 713.2 expected, observed/expected ratio (o/e) 0.62, 90% interval 0.57 to 0.67. Synonymous variants: 239 observed, 261.98 expected, observed/expected ratio (o/e) 0.91, 90% interval 0.82 to 1.01.
Homologues: Orthologues: macaque GAD1 (99% identical), chimpanzee GAD1 (99% identical), dog GAD1 (98% identical), pig GAD1 (98% identical), mouse Gad1 (97% identical), guinea pig GAD1 (97% identical), rabbit GAD1 (95% identical), rat Gad1 (94% identical), tropical clawed frog gad1 (88% identical), zebrafish gad1b (83% identical), zebrafish gad1a (80% identical), Drosophila melanogaster Gad1 (50% identical), and 3 more. Paralogues in human: GAD2 (64% identical), CSAD (43% identical), GADL1 (42% identical), HDC (20% identical), DDC (18% identical), SGPL1 (16% identical), PDXDC1 (15% identical).
Diseases named in the same sentence as GAD1 in open-access papers:
GAD1 is named in the same sentence as 253 diseases in open-access papers, as found by Europe PMC text mining. Sharing a sentence is not in itself a finding about the gene and the disease. The quoted sentences say what the papers report.
schizophrenia (189 papers, 2007 to 2026). A major psychotic disorder characterized by abnormalities in the perception or expression of reality. "Glutamate decarboxylase 1(GAD1) is animportant regulator of glutamate, and some common polymorphisms have been found tobe more represented in schizophrenia patients." (PMID 40527340, 2025). "Approximately 60% of the observed decreases in 5mC occurred in the promoter regions of genes, including schizophrenia susceptibility genes such as GAD1 and glutamate metabotropic receptor 7 (GRM7)." (PMID 38203806, 2024). "GAD1 mutations are associated with neurodegenerative diseases such as schizophrenia, bipolar disorder, and other movement disorders, and Gad67−/− knockout mice display neonatal death." (PMID 36835631, 2023). "The level of the GABA synthetic enzyme glutamate decarboxylase 67 kDa isoform (GAD67) encoded by the GAD1 gene is downregulated in the brains of schizophrenia patients." (PMID 35269691, 2022). "Researchers have specifically targeted the glutamate decarboxylase 1 (GAD1) gene-encoded 67-kDa protein isoform of GAD67 as a hallmark of schizophrenia in Pv-FS sin transgenic mice." (PMID 34220586, 2021). "Reduced expression of glutamate decarboxylase 67 (GAD67), encoded by the Gad1 gene, is a consistent finding in postmortem brains of patients with several psychiatric disorders, including schizophrenia, bipolar disorder and major depressive disorder." (PMID 33413507, 2021). "The GABA synthetic enzyme glutamate decarboxylase 67-kDa isoform (GAD67) encoded by the GAD1 gene is downregulated in the brains of patients with schizophrenia." (PMID 33293518, 2020). "Based on these genetic findings combined with accumulated evidence from postmortem brain studies, we can assume that loss-of-function mutations of Gad1 have a causal effect on the symptoms of schizophrenia, particularly on cognitive impairment." (PMID 33293518, 2020). "Despite the fact that a number of investigations concerning associations between COMT and GAD1 genes with schizophrenia have been performed, the conclusions from these reports are somewhat open to debate." (PMID 29429137, 2018). "Three single nucleotide polymorphisms at 5’ regulatory region of GAD1 have been associated with decreased expression levels, increased risk for childhood-onset schizophrenia and cortical gray volume loss." (PMID 28122016, 2017). "Common polymorphisms in the proximal GAD1 promoter have also been suggested to act as genetic risk factors for schizophrenia." (PMID 28787007, 2017). "A reduction in GAD1 expression at prefrontal cortex of people with schizophrenia was observed to be associated with three DNA methylation sites at GAD1." (PMID 28122016, 2017). "Our suggested interpretation is compatible with results from patients with schizophrenia, mood disorders, and Parkinson’s disease, in whom neocortical GAD1 mRNA is abnormally expressed and loss of inhibitory neurons is not observed." (PMID 26829944, 2016). "Genetic variants in the GAD1 gene are associated with increased risk for schizophrenia, and reduced expression of its major transcript in the human dorsolateral prefrontal cortex (DLPFC)." (PMID 26848839, 2016). "For instance, SNPs in the 5′ regulatory region of the Gad1 gene (coding for the GABA- synthesizing enzyme GAD67) are associated with childhood onset schizophrenia." (PMID 21826279, 2011). "These two SNP's are included in a GAD1 haplotype that confers genetic risk for childhood-onset schizophrenia and accelerated loss of frontal gray matter." (PMID 17726539, 2007). "Based on these findings, decreased GAD1 mRNA expression in interneurons of schizophrenia subjects would be predicted to be associated with increased DNA methylation." (PMID 17726539, 2007). "Furthermore, a schizophrenia patient harboring a homozygous mutation of GAD1 has recently been discovered." (PMID 35269691, 2022). "Alternative splicing of GAD1 and the epigenetic state may play roles in brain development and the risk of schizophrenia." (PMID 33413507, 2021).
schizophrenia (continued). "Therefore, it should be noted that the evidence of an association between the genetic variation of GAD1 and schizophrenia is limited." (PMID 33293518, 2020). "Therefore, herein, we focused on the behavioral characterization of global Gad1 KO rats to provide evidence supporting the cause-effect relationship between loss of function of GAD67 and schizophrenia-related phenotypes, including cognitive impairment." (PMID 33293518, 2020). "Furthermore, homozygous missense mutations in the GAD1 gene were identified in a family of schizophrenia patients by whole-exome sequencing in Italy24,25." (PMID 33293518, 2020). "To test the hypothesis that loss-of-function mutation in the GAD1 gene leads to cognitive impairments observed in schizophrenia, we generated Gad1 KO rats using genome editing." (PMID 33293518, 2020). "Furthermore, a patient with schizophrenia harboring a homozygous mutation of GAD1 has recently been discovered." (PMID 33293518, 2020). "Huang and Akbarian found an average 8-fold deficit in repressive chromatin-associated DNA methylation at GAD1 promoters in patients with schizophrenia and it has been shown that histone 3 (H3), one of the histone proteins, was particularly dysregulated in schizophrenia patients." (PMID 29991943, 2018). "For example, the level of Gad1 mRNA encoding GAD67 (glutamic acid decarboxylase-67) falls below detectable levels in approximately 50% of parvalbumin (PV)-positive prefrontal cortex (PFC) interneurons in schizophrenia." (PMID 29362511, 2018). "However, genome-wide association studies (GWAS) have confirmed relatively few of these associations though a post-GWAS has identified not only COMT but also GAD1 among a selection of schizophrenia risk genes." (PMID 29429137, 2018). "Furthermore, several studies on schizophrenia also revealed gender differences in associations of GAD1 SNPs." (PMID 22662185, 2012). "Moreover, allelic variations in Gad1 have been shown to associate with schizophrenia and to influence multiple domains of cognition, including declarative memory, attention and working memory." (PMID 21826279, 2011). "Instead of or in addition to medication effects, the large variability in cortical GABA content measured with MRS in human cortex may be explained by the effects of genetic variants in the GAD1 gene that may differentially confer risk of schizophrenia." (PMID 21904685, 2011). "Therefore, repressive chromatin-associated histone methylation at the GAD1 locus in schizophrenia appears to be, at least in part, independent from CpG methylation." (PMID 17726539, 2007). "Therefore, the deficit in prefrontal GAD1 mRNA levels in this cohort of schizophrenia subjects is associated with a selective decrease in DNA methylation in repressive GAD1 chromatin at the site of the proximal gene promoter." (PMID 17726539, 2007). "Looking at the results of animal studies, we speculate this decrease could be caused by exposure to schizophrenia-associated environmental risk factors, as a mouse study revealed that maternal immune activation increases Gad1 promoter methylation, which is accompanied by reduced mRNA expression." (PMID 32764320, 2020). "However, it remains unclear whether loss of function of GAD1 leads to the symptoms observed in schizophrenia, including cognitive impairment." (PMID 33293518, 2020). "In fact, patients with schizophrenia have increased 5mC in the GAD1 promoter region, resulting in decreased expression." (PMID 38203806, 2024). "In patients with schizophrenia, 5mC levels in the promoter region of GAD1 were reduced, resulting in a significant increase in the overall expression of GAD1." (PMID 38203806, 2024). "In contrast, smaller genetic studies have shown that single nucleotide polymorphisms (SNPs) and loss-of-function mutations in the GAD1 gene were involved in GAD67 expression levels and schizophrenia." (PMID 37168420, 2023).
schizophrenia (continued). "Clozapine, but not haloperidol or risperidone, corrects behavioural phenotypes and normalized the DNMT1 level and 5-mC promoter hypermethylation of schizophrenia-related genes (GAD1, RELN, BDNF) in the PRS animal models." (PMID 36979236, 2023). "In summary, while the phenotype of Gad1–/– mice exhibits some similarities to schizophrenia, the effect it has on working memory remained inconclusive." (PMID 37168420, 2023). "Most schizophrenia cases carrying GIT1 variants fail to induce PAK3 activation and GAD1, the key enzyme in GABA biosynthesis, in neurons, suggesting the contribution of PAK3 dysregulation in the synaptic deficits in schizophrenia." (PMID 33306168, 2022). "In the cortex, schizophrenia cases with a high inflammatory biotype have lower GAD1, SST, and PV mRNAs when compared to schizophrenia cases with the low inflammatory biotype." (PMID 34174930, 2021). "A study also demonstrated that methylation levels of two CpG loci within the putative GAD1 promoter was significantly associated with the expression of GAD25 in the DLPFC and with the SNP rs3749034, a SNP associated with schizophrenia." (PMID 34746116, 2021). "Glutamate decarboxylase 1 (GAD1) was found to be hypomethylated from the prefrontal cortex of schizophrenia cases." (PMID 34831111, 2021). "Gad1−/− rats will represent a novel tool to study pathophysiology and to develop treatments for cognitive impairment in schizophrenia." (PMID 33293518, 2020). "Consistent with the findings presented here, previous studies reported changes in DNA methylation within the Gad1 and Ntrk2 gene promoters in rodent models of stress and humans suffering from schizophrenia, bipolar disorder, or depression." (PMID 30874581, 2019). "Cultured cells, mouse cortex, or striatum was harvested, RNA extracted and RT-PCR conducted for several schizophrenia candidate genes: IL-6, Gad1, Nanog, KLF4, Reln, and Bdnf9a." (PMID 31185023, 2019). "Taken together, these results suggested that male mutant mice do not display cognitive or positive symptom-like phenotypes of schizophrenia, consistent with the conclusion reported for PV-neuron/Gad1 KO mice." (PMID 29362511, 2018). "Downregulation of hippocampal BDNF-TrkB signaling in schizophrenia and mood disorders is accompanied by changes in glutamate decarboxylase 1 (GAD1), an enzyme involved in production of GABA from glutamate." (PMID 28872625, 2017). "Of the “best candidate” genes, this is the most intriguing, because reduced GAD1 mRNA and protein levels have been consistently observed in post-mortem brains of schizophrenia patients." (PMID 28787007, 2017). "A previous study reported that long-term medication for schizophrenia decreased DNA methylation of the GAD1 promoter, which was hypermethylated in a mouse model of schizophrenia." (PMID 28149334, 2017). "Two genes, GAD1 and GAD2, control GABA synthesis, but only the former has been clearly implicated in schizophrenia." (PMID 26848839, 2016). "Down-regulated levels of GAD1 mRNA and GAD67 protein are characteristic features of various neurocognitive and psychiatric disorders, including autism, bipolar disorder, epilepsy, and schizophrenia." (PMID 26829944, 2016). "Previous work from our group has demonstrated the importance of alternate transcripts from GAD1 in both early brain development and schizophrenia." (PMID 26848839, 2016). "A neurodevelopmental origin for schizophrenia is shown from the study suggesting increased methylation and reduced Gad1 expression in rats which fits with the observations in postmortem brains of schizophrenic patients." (PMID 26583053, 2015). "Early studies of mRNA expression in post mortem tissue identified a decrease in Gad1 mRNA (coding for the Gad67 protein) in the prefrontal cortex of individuals with schizophrenia or bipolar disorder." (PMID 25116473, 2014). "The reduction of GAD1 observed in our data is one of the most consistent changes in the schizophrenia neocortex." (PMID 22558445, 2012).
schizophrenia (continued). "It is of interest that GAD1 has also been shown to be down-regulated in the hippocampus of patients with schizophrenia and bipolar disorder." (PMID 22253714, 2012). "Post-mortem studies of patients with schizophrenia consistently show reduced levels of the mRNA for the 67-kD isoform of glutamic acid decarboxylase (GAD67, encoded by GAD1), a key factor in optimal GABA levels, in the DLPFC of patients with schizophrenia." (PMID 23091464, 2012). "This DNA methylation deficit in repressive GAD1 chromatin of schizophrenia subject affected 5/8 GpG nucleotides and was significant (Wilcoxon Signed Ranks Test, p = 0.018)." (PMID 17726539, 2007). "Given that DNA methylation around the proximal promoter typically contributes to transcriptional repression, it was expected that subjects with schizophrenia show increased GAD1 DNA methylation." (PMID 17726539, 2007). "Next, we monitored GAD1 CpG methylation levels in subjects diagnosed with schizophrenia and their matched controls." (PMID 17726539, 2007). "Dysfunction of prefrontal cortex in schizophrenia includes changes in GABAergic mRNAs, including decreased expression of GAD1, encoding the 67 kDa glutamate decarboxylase (GAD67) GABA synthesis enzyme." (PMID 17726539, 2007). "Second, allelic polymorphisms within GAD1, the gene encoding GAD67, confer genetic risk for childhood-onset schizophrenia and accelerated loss of frontal gray matter." (PMID 17726539, 2007). "Modifications in the expression of Gad1 has been investigated in relation to some brain disorders, since Gad1 mRNA decreased in prefrontal cortex and other brain areas of schizophrenia and bipolar disorder patients with psychosis." (PMID 18062813, 2007). "Instead, we observed for the repressive chromatin fraction of schizophrenia subjects a significant decrease in CpG methylation at the proximal GAD1 promoter." (PMID 17726539, 2007). "GAD1 expression is also robustly found to be decreased in PFC in schizophrenia." (PMID 41317238, 2025). "Many studies found consistent alterations in GAD1 mRNA expression in schizophrenia." (PMID 37131313, 2023). "Furthermore, the ratios are associated with the rs3749034 genotype which is a risk-associated promoter SNP in GAD1, an enzyme involved in GABA synthesis, overall suggesting abnormal GABA signaling in development is a genetic risk for schizophrenia." (PMID 36771011, 2023). "Although this reduction may be too extreme compared with schizophrenia patients, Gad1–/– rats are expected to be a good experimental system to investigate the extent to which reduced tissue GABA levels affect microglial properties." (PMID 37168420, 2023). "Furthermore, increased gene expression of the viral restriction factor interferon-induced transmembrane protein (IFITM) is linked to lower expression of GABA-related mRNAs, including GAD1 and SST, in the cortex of schizophrenia cases." (PMID 34174930, 2021). "Based on these findings, we speculated that Gad1 haplodeficiency combined with chronic NMDA receptor blockade would lead to larger behavioral consequences relevant to schizophrenia in a rat model." (PMID 33859565, 2021). "As opposed, a mouse model with GAD1 genetically ablated within ~50% cortical and hippocampal interneurons resulted in a subset of negative symptoms with reduced willingness to expend costly effort, as noticed in patients with schizophrenia." (PMID 34055795, 2021). "Functional impairment of both types of PV (basket and chandelier) containing interneurons including the reduced expression of parvalbumin, GABA transporter (GAT)-1 mRNAs, and Gad1 (GAD67) all contribute to schizophrenia development (Lewis and González-Burgos, 2008)." (PMID 34055795, 2021).